CCNE1 (cyclin E1)
Diseases named in the same sentence as CCNE1 in open-access papers (continued):
Sharing a sentence is not in itself a finding about the gene and the disease.
ovarian carcinoma (continued). "The investigators observed that cyclin E1 (CCNE1) was overexpressed in 30% of established ovarian cancer cell lines, and such cancer cells were 40 times more sensitive to SNS-032 therapy, a CDK2 small molecule inhibitor." (PMID 38612869, 2024). "We treated a panel of ten ovarian cancer cell lines (including five HGSOC with CCNE1 amplification) with either INX-315 or palbociclib for six days, allowing for multiple doubling times before assessment of cell viability." (PMID 38047585, 2024). "We propose that CCNE1-amplified ovarian cancer cells rely on HR to resume replication after fork collapse." (PMID 37519629, 2023). "The present study identifies variations in copy numbers of CCNE1 as marker of chemo-resistance in ovarian cancers." (PMID 37250533, 2023). "A study in BRCAwt, CCNE1 amplified platinum-resistant ovarian cancer patient-derived xenograft (PDX) models showed that the combination of PARPi and ATRi results in tumor reduction and a significant increase in OS." (PMID 37842243, 2023). "Region 20q13.12, previously identified in other ovarian tumors, was amplified in our cohort, along with other genes that have previously found amplified in ovarian cancer such as CCNE1, ERBB2, RSF1 and deleted genes like BRCA18,22." (PMID 37400526, 2023). "RP-6306, a highly selective inhibitor of this target, was tested on several ovarian carcinoma cell lines and showed greater toxicity in CCNE1 amplified preclinical models alone or with gemcitabine." (PMID 37842243, 2023). "CCNE1 amplification has been proposed as a biomarker of intrinsic resistance to platinum-based chemotherapy in ovarian cancer." (PMID 37457127, 2023). "To test if a CDK2 inhibitor in combination with etoposide is anti-tumorigenic in vivo, we used the OVCAR-3 xenograft, a model previously used to validate CDK2 as an oncogenic driver in CCNE1-amplified ovarian cancer." (PMID 37519629, 2023). "S-phase is prolonged when CCNE1 is overexpressed or amplified in an E2F dependent manner in ovarian cancer cells." (PMID 36499727, 2022). "Consistent with this idea, the analysis of VCP knockout effects in ovarian cancer cells from the Dependency Map project indicates CCNE1-amplified cells, such as COV318, ONCODG1, OVCAR3, and SNU8, show strong dependency on VCP." (PMID 35740614, 2022). "Consistently, in this study, exogenously expressed of HK2 also promoted cell growth in human ovarian cancer cells by accelerating cell cycle progression (up-regulated the expression of cell cycle-related factors, like cyclin A1, cyclin D1 and cyclin E1)." (PMID 35953860, 2022). "CCNE1, which functions as the regulator for the transition from G1 to S phase and determines cell division, mainly was amplificated in the HR-proficient ovarian cancer cells." (PMID 35372049, 2022). "In ovarian cancer, CCNE1 amplification is detected in about 20% of tumours, in a manner largely mutually exclusive with homologous recombination deficiency, and is enriched in platinum-refractory tumours." (PMID 35444283, 2022). "Another study also identified VCP as one of the essential genes in cyclin E1 (CCNE1) amplified ovarian cancer cells." (PMID 35740614, 2022). "Our findings of shorter OS in patients with CCNE1 are in line with other studies that have found a correlation between CCNE1 amplification in epithelial ovarian cancer and poor outcomes." (PMID 36612212, 2022).
ovarian carcinoma (continued). "Despite the role of CCNE1 in the proliferation of normal cell lines, it has been reported as a biomarker for chemotherapy resistance in ovarian cancer and for prognosis in breast cancer." (PMID 35468924, 2022). "CCNE1 amplified tumors accounted for 19% of all ovarian cancer samples included in the TCGA PanCan 2018 dataset." (PMID 36612212, 2022). "SNF2H can only bind with cyclin E1 in RSF1 expression-induced SKOV3 ovarian cancer cells, implying that cyclin E1 binds with SNF2H through direct binding with RSF1." (PMID 34147108, 2021). "Specifically, VCP/p97 was identified as an essential gene in ovarian cancer cells and in cyclin E1-overexpressing cisplatin-resistant ovarian cancer cells." (PMID 34576340, 2021). "CCNE1 amplification has been found in a number of malignancies including sarcomas, non-small cell lung cancer, leukemia, lymphoma, breast and ovarian cancers." (PMID 34485660, 2021). "Cyclin E1 is a cell cycle regulator, and cyclin E1-driven ovarian cancer is characterized by decreased cancer immunity mediated by activated polyamine synthesis." (PMID 34177954, 2021). "More than 20 CDK inhibitors exist and have been tested on CCNE1 amplified ovarian cancer cell lines with inconsistent efficacy and proposed resistance mechanisms including an increase in pro-survival signaling." (PMID 34485660, 2021). "CCNE1 amplification has been identified as a predictive biomarker of poor chemotherapy response in epithelial ovarian cancer and other cancers." (PMID 32380689, 2020). "In terms of frequency, the cyclin E1 gene is one of the most commonly amplified genes in ovarian cancer (19%), anaplastic thyroid cancer (29%) and osteosarcoma (27-33%)." (PMID 33282745, 2020). "Exploring the interplay between cyclin E1 amplification and other common ovarian cancer genetic alterations provides the basis for understanding chemotherapeutic resistance in CCNE1 amplified disease." (PMID 32380689, 2020). "Multivariable ovarian cancer specific survival analyses of CCNE1 subgroups of HGSC defined by combination of copy number and protein expression status." (PMID 32391646, 2020). "VCP is an ovarian cancer-specific essential gene as demonstrated by a pooled short hairpin RNA (shRNA) screen in 25 ovarian cancer cell lines, and is also essential in cyclin E1 overexpressing cisplatin-resistant ovarian cancer cells." (PMID 32404140, 2020). "Understanding the interplay between cyclin E1 amplification and other common ovarian cancer genetic alterations provides the basis for chemotherapeutic resistance in CCNE1 amplified disease." (PMID 32380689, 2020). "One such study identified CCNE1 amplification in 18 (20.4%) of 88 ovarian carcinomas included in the study and found that the presence of CCNE1 amplification correlated with shorter disease-free survival and overall survival (p < 0.001)." (PMID 32380689, 2020). "Few studies have specifically investigated CCNE1 amplification status as a predictive biomarker of chemotherapy response in ovarian cancer." (PMID 32380689, 2020). "The primary objective of this study was to review the relationship between CCNE1 amplification and cytotoxic chemotherapy resistance and evaluate CCNE1 amplification as a predictive biomarker in ovarian cancer." (PMID 32380689, 2020). "When we analysed the ploidy of TCGA ovarian cancers, we found, as expected, that CCNE1 occurred at significantly higher levels in whole genome doubled tumours versus non-genome doubled, although CCNE2 did not." (PMID 32823571, 2020). "Several studies have correlated CCNE1 amplification in epithelial ovarian cancer with poor outcomes." (PMID 32380689, 2020). "The anticancer effect of Cyclin E1/Cdk2 complexes has been extensively concerned in a variety of tumors, including ovarian cancer, liver cancer, and so on." (PMID 33537306, 2020). "CCNE1 amplified tumors account for 19.01% of all ovarian cancer samples included in The Cancer Genome Atlas (TCGA) PanCan 2018 dataset." (PMID 32380689, 2020).
ovarian carcinoma (continued). "Consideration of the interplay between cyclin E1 amplification and other common ovarian cancer genetic alterations provides the basis for understanding chemotherapeutic resistance in CCNE1 amplified disease." (PMID 32380689, 2020). "Cyclin E1 is overexpressed in up to 50% of HGSOC cases, and CCNE1 silencing reduces ovarian cancer cell viability." (PMID 33014878, 2020). "Next, the PI3K pathway leads to CCNE1 overexpression which leads to ovarian cancer cell growth and survival." (PMID 30944378, 2019). "Due to the amplification of genes, Cyclin E1 RNA is overexpressed in 29.5% and CKD2 in 6.5% of ovarian tumors tested, making it another hallmark of ovarian cancer besides BRCAness." (PMID 31313989, 2019). "Combination therapy targeting both CDK2 and GCN5 hold promise for combating Cyclin E1‐driven ovarian cancer." (PMID 31657115, 2019). "In this study, we sought to evaluate the association of HR pathway mutations, HR deficiency scores and CCNE1 and RB1 CNA with response to platinum retreatment in ovarian cancer patients in the platinum-resistant setting." (PMID 31060523, 2019). "Our previous reports indicate that Cyclin E1-driven ovarian cancer is sensitive to inhibition of both CDK2 and glucose metabolism." (PMID 31313989, 2019). "In the current study, we have provided evidence that CCNE1 drives metabolic alteration in ovarian carcinoma with activated GCN5/PGC-1α signaling." (PMID 31313989, 2019). "Cyclin E1, is found to be overexpressed in various cancers including ovarian cancer and hence considered as a biomaker." (PMID 30581772, 2018). "Primary treatment failure (platinum-based chemotherapy) in ovarian cancer was attributed to CCNE1 amplification and partly to an intact BRCA1/2 pathway." (PMID 27582547, 2017). "CCNE1-amplified ovarian cancer cells were more sensitive to cell cycle arrest, growth inhibition and apoptosis induction by CCNE1 siRNA." (PMID 27582547, 2017). "For example, cyclin E1 (CCNE1) in the LMCT-7 module has been shown to promote metastasis of ovarian cancer and bladder cancer." (PMID 28628609, 2017). "A recent study on the whole-genome characterisation of chemoresistant ovarian cancer by The Australian Ovarian Cancer Study Group showed that CCNE1 amplification is common in primary resistant and refractory disease." (PMID 27833130, 2016). "Our results support the notion that CCNE1 gene amplification is at least one of the key factors contributing to elevated CCNE1 expression in ovarian cancer." (PMID 26204491, 2015). "CCNE1 amplification/overexpression is mutually exclusive to BRCA1 deletion/underexpression in ovarian cancers (p-value = 0.073)." (PMID 26427375, 2015). "This PM has two genes (RB1 and CCNE1) in the well-characterized RB1 cancer pathway that plays important roles in ovarian cancer tumorigenesis." (PMID 26317392, 2015). "Our results are also in agreement with two recent studies reporting that depleting CCNE1 leads to the suppression of ovarian cancer cell proliferation." (PMID 26204491, 2015). "We also showed that knockdown of CCNE1 led to the suppression of cell growth of ovarian cancer cells with inherently elevated CCNE1 expression." (PMID 26204491, 2015). "Previous studies reveal that CCNE1 gene amplification correlates with tumor progression and predicts a poor prognosis in ovarian cancer patients." (PMID 26204491, 2015). "Immunohistochemistry studies with both primary and metastatic ovary tumor specimens further show that the abundance of cyclin E1 (CCNE1) correlates with tumor progression and predicts a poor prognosis in ovarian cancer patients." (PMID 26204491, 2015). "In fact, forced CCNE1 expression accelerates cell growth and increases chemosensitivity in ovarian cancer cells." (PMID 26204491, 2015). "Here, we showed that Cyclin E1 (CCNE1) was overexpressed in 30% of established ovarian cancer cell lines." (PMID 26204491, 2015).
ovarian carcinoma (continued). "An early study reported that high CCNE1 expression is a significant and independent predictor for prolonged overall survival in late stage ovarian cancer patients." (PMID 26204491, 2015). "Here, we show that elevated CCNE1 expression is detected in more than 30% of the established ovarian cancer cell lines and majority of the lines with CCNE1 overexpression displayed CCNE1 gene amplification." (PMID 26204491, 2015). "With a panel of established ovarian cancer cell lines, we found that majority of ovarian cancer cells lines with CCNE1 overexpression possessed CCNE1 gene amplification." (PMID 26204491, 2015). "In this study, we show that ovarian cancer cell lines with elevated CCNE1 expression are at least 40 times more sensitive to Cdk2 inhibitor SNS-032 than lines without inherent CCNE1 overexpression, non-cancerous OECs and FTSECs." (PMID 26204491, 2015). "In ovarian cancer cells, enforcing CCNE1 expression stimulates cell proliferation and increases colony formation." (PMID 26204491, 2015). "In ovarian cancer, CCNE1 gene was amplified in approximately 20% of ovary tumor specimens including both serous and endometrioid types." (PMID 26204491, 2015). "This possibility is supported by our observation that Cdk2 inhibitor SNS-032 suppressed metastatic colonization of CCNE1-overexpressing ovarian cancer cells and greatly prolonged the survival of mice bearing ovary tumors with CCNE1 overexpression." (PMID 26204491, 2015). "SNS-032 apparently inhibits cell growth of inherently CCNE1-overexpressing ovarian cancer cells by inducing apoptosis." (PMID 26204491, 2015). "Genetic depletion of BRCA1 resulted in significant loss of viability in CCNE1-amplified cells, including the ovarian cancer cell line OVCAR3, whereas a lesser effect was observed in CCNE1-wildtype cells, such as the SKOV3 cell line." (PMID 24624361, 2014). "Our unpublished data show that Dinaciclib exposure results in downregulation of BRCA1 and BRCA2 and sensitized cyclin E1-dependent ovarian cancer cells to cisplatin." (PMID 24624361, 2014). "Cell cycle regulators, such as CCNE1 (10–20 copies in ovarian cancer), were also highly amplified, as expected." (PMID 24874471, 2014). "For instance, the ovarian cancer oncogenes CCNE1 and RAB25 show significant methylation and expression correlation for both amplified and deleted copy number aberrations." (PMID 22174824, 2011). "Correlating changes of CNV and expression can be seen in genes of the ovarian cancer 19q amplicon CCNE1 (r = 0.73) and AKT2 (r = 0.66), suggesting functional variation within the ovarian cancer sample population." (PMID 22174824, 2011). "We performed the first systematic siRNA knockdown of all genes within the minimally defined 19q12 amplicon in ovarian cancer showing that CCNE1 is the key oncogenic target." (PMID 21103391, 2010). "CCNE1 (Cyclin E) has previously been suggested as the target of amplification in ovarian cancer, however a systematic analysis of known genes within the amplicon has not been performed." (PMID 21103391, 2010). "For example, over-expression of CCNE1 in vitro renders ovarian cancer cells more sensitive to platinum agents, presumably due to increased proliferation." (PMID 21103391, 2010). "CCNE1 amplification was identified in 8.01% of the patients with ovarian cancer." (PMID 41331376, 2025). "For example, CCNE1 amplification/gain, which is a predictive biomarker of PARPi and platinum-based treatment resistance in epithelial ovarian cancers, is mutually exclusive with a pathogenic BRCA1/2 mutation in ovarian cancers." (PMID 39985088, 2025). "In the TCGA ovarian cancer dataset, we observed that CCNE1 expression levels and CCNE1 copy number status correlated negatively with ploidy-score, aneuploidy-scores, and genome doubling, while both showed a negative correlation to the PARPi7-score and different HRD-scores." (PMID 41034557, 2025).
ovarian carcinoma (continued). "We hypothesized that the increased BRD4 copy-number in these samples may be due to large-scale amplifications involving cyclin E1 (CCNE1), a known driver in endometrial, breast, and ovarian cancers, which is also located on chromosome 19." (PMID 40112818, 2025). "CDK2 targeting in cyclin-E1-overexpressing ovarian cancer will have a positive clinical impact." (PMID 38612869, 2024). "Cyclin-dependent kinases (CDK2, CDK4, CDK6), cyclin D1, cyclin E1 and phosphorylated retinoblastoma (pRB1) are key regulators of the G1/S cell cycle checkpoint and may influence platinum response in ovarian cancers." (PMID 38612869, 2024). "Interestingly, cytoplasmic expression of CDK4, cyclin D1 and cyclin E1 also has predictive and/or prognostic significance in ovarian cancers." (PMID 38612869, 2024). "Amplification of the CCNE1 is common in many cancers, especially in breast and ovarian carcinomas." (PMID 38279263, 2024). "Amplifications of CCNE1 are known to indicate a poor prognosis in ovarian cancer." (PMID 38036971, 2023). "We also observed that CCNE1-amplified cells tend to have higher levels of aneuploidy compared with non-amplified cell lines across tumor types (P = 2.2 × 10−9), and in ovarian cancer cell lines specifically (P = 0.0044)." (PMID 37519629, 2023). "Given that VCP has also been shown to be an essential gene in CCNE1 amplified ovarian cancer cells, future studies could analyze if CB-5083 and mifepristone combination display enhanced synergistic cytotoxicity in CCNE1 amplified ovarian cancer cells." (PMID 35740614, 2022). "Expression of CCNE1 has been reported in various cancers such as bladder cancer, colorectal cancer, gastric, high-grade serous ovarian carcinomas (HGSCs) and ovarian cancer." (PMID 36139498, 2022). "Additionally, a higher prevalence of gain 19q12 in patients with high-IPR score was identified, namely, locus encoded cyclin E1 (CCNE1) and URI1, and has been previously identified to be associated with chemoresistance in ovarian cancer patients." (PMID 35372049, 2022). "Cyclin E1 amplification occurs in 19.1% of all ovarian cancers and 3.4% of breast cancers." (PMID 34711195, 2021). "Recent study has found that the CCNE1 gene could serve as an oncogene and a poor prognostic factor in ovarian cancer and lung cancer." (PMID 34663408, 2021). "Cyclin-E1 (CCNE1) gene amplification is presented in 15% of ovarian cancers." (PMID 34680987, 2021). "Thus, CCNE1 amplification seems to be a valuable prognostic biomarker in ovarian cancer and across other cancer subtypes." (PMID 32380689, 2020). "One study found that CCNE1 amplification correlates with chemoresistance in ovarian cancer." (PMID 32380689, 2020). "The URI1 gene (HGSC vs EC comparison), involved in ubiquitination and transcription, spans the same genomic region as CCNE1, and has also been reported to be amplified in ovarian carcinoma and may contribute to tumorigenesis." (PMID 32409713, 2020). "For example, targeting Cyclin E1 by a PLK1 inhibition-based stabilization of FBW7 might be a novel approach to increase apoptosis in CCNE1-amplified ovarian cancer cells." (PMID 32380689, 2020). "The cyclin E1 gene (CCNE1) is commonly amplified or gained in ovarian cancer." (PMID 32044108, 2020). "Meanwhile, in the analysis of ovarian cancer data from TCGA, NAMDD found 389 significant path associations, among which, we investigated and explained the disease pathogenesis mechanisms, including the CCNE1, AURKA, and RAB25 genes." (PMID 30944378, 2019). "A subset of ovarian cancer is known to overexpress CCNE1 or CCND1, suggesting that cell-cycle-targeted drugs such as palbociclib, a CDK4/6 inhibitor, may be effective in specific subsets of ovarian cancer." (PMID 31052165, 2019). "Ovarian cancer samples with no CCNE1 CN gains were associated with higher response rate compared with cases with CCNE1 CN gains (ORR = 83.3 vs 22.2%; p = 0.041)." (PMID 31060523, 2019).